RN7SL149P (RNA, 7SL, cytoplasmic 149, pseudogene)
Gene: Miscellaneous RNA gene on chromosome 8 (41,840,059 to 41,840,339, reverse strand). Ensembl gene ENSG00000241834.
Homologues: Orthologues: chimpanzee Metazoa_SRP (99% identical), macaque Metazoa_SRP (88% identical). Paralogues in human: RN7SL1 (86% identical), RN7SL2 (86% identical), RN7SL3 (85% identical), RN7SL679P (83% identical), RN7SL664P (82% identical), Metazoa_SRP (81% identical), RN7SL220P (81% identical), RN7SL448P (81% identical), RN7SL566P (81% identical), RN7SL732P (81% identical), RN7SL769P (81% identical), RN7SL230P (81% identical), and 703 more.